METTL3 (methyltransferase 3, N6-adenosine-methyltransferase complex catalytic subunit)
Diseases named in the same sentence as METTL3 in open-access papers (continued):
Sharing a sentence is not in itself a finding about the gene and the disease.
cholangiocarcinoma (13 papers, 2021 to 2025). A carcinoma that arises from the intrahepatic biliary tree (intrahepatic cholangiocarcinoma) or from the junction, or adjacent to the junction, of the right and left hepatic ducts (hilar cholangiocarcinoma). "Interferon-induced protein with tetratricopeptide repeats 2 (IFIT2) has also been identified as a target of METTL3 in cholangiocarcinoma." (PMID 38365891, 2024). "Recent evidence showed that METTL3 promotes cholangiocarcinoma progression by YTHDF2-mediated IFIT2 mRNA degradation." (PMID 38267969, 2024). "Previous evidence suggests that METTL3 mediates IFIT2 mRNA decay in an m6A-dependent manner to inhibit the progression of intrahepatic cholangiocarcinoma." (PMID 37194218, 2023). "We aimed to excavate the biological role and mechanism of the m6A methyltransferase METTL3 in cholangiocarcinoma (CCA)." (PMID 36476503, 2022). "In contrast, NKILA interacts with mir-582-3p regulated by m6A methyltransferase METTL3 and inhibits its expression, thereby accelerating cholangiocarcinoma progression through YAP1." (PMID 36333719, 2022). "Interestingly, METTL3 was recently reported to regulate IFIT2 expression in a m6A-YTHDF2-dependent manner in cholangiocarcinoma." (PMID 36386128, 2022).
triple-negative breast carcinoma (13 papers, 2020 to 2025). An invasive breast carcinoma which is negative for expression of estrogen receptor (ER), progesterone receptor (PR), and human epidermal growth factor receptor 2 (HER2). "In TNBC, METTL3 is an important collaborator in regulating metastasis, and low expression of METTL3 is implicated in the poor prognosis of triple-negative breast cancer (TNBC)." (PMID 36035182, 2022). "Conversely, poor prognosis of the triple-negative breast cancer (TNBC) was associated with lower expression of METTL3, suggesting the tumor suppressing role of METTL3." (PMID 33879256, 2021). "The expression of METTL3 in normal tissue was significantly lower than that in triple negative breast cancer (TNBC) according to The Cancer Genome Atlas (TCGA) database." (PMID 39800682, 2025). "In the current study, we explored the mechanism about METTL3/LINC00662/miR-186-5p feedback loop regulates docetaxel resistance in Triple negative breast cancer." (PMID 36202872, 2022). "We aimed to investigate the role of N6-methyladenosine (m6A) and the METTL3/LINC00662/miR-186-5p pathway in regulating docetaxel resistance in triple negative breast cancer (TNBC)." (PMID 36202872, 2022). "Six paired samples from two luminal B, two Her2 enriched, and two triple-negative breast cancer (TNBC) patients were used for IHC of METTL3, METTL14, FTO, YTHDF1, and YTHDF3." (PMID 34804948, 2021). "Therefore, circMETTL3 inhibits the tumor growth of triple negative breast cancer via miR-34c-3p/METTL3 signaling." (PMID 35004298, 2021). "In addition, the low expression of METTL3, an important m6A writer, was found to be correlated with the poor prognosis of triple-negative breast cancer (TNBC), and METTL3 might serve as a novel therapeutic target in TNBC metastasis." (PMID 35003212, 2021). "In triple-negative breast cancer (TNBC), METTL3 expression was relatively low; restoring METTL3 increased m6A on the COL3A1 mRNA, which led to reduced COL3A1 expression and impaired invasion." (PMID 41301491, 2025).
chronic myeloid leukemia (12 papers, 2021 to 2025). "Recently, METTL3 was proved to sustain aberrant ribosome level and translation to regulate the cell proliferation in chronic myeloid leukemia." (PMID 38267969, 2024). "Meanwhile, METTL3-modified lncRNA NEAT1 inhibits the progression of chronic myeloid leukemia (CML) by downregulating miR-766-5p targeting cyclin-dependent kinase inhibitor 1A (CDKN1A)." (PMID 38351139, 2024). "Specifically, METTL3 regulates PTEN mRNA instability to reduce PTEN protein expression and cause continuous activation of the PI3K/AKT pathway in chronic myelocytic leukemia cells." (PMID 34315512, 2021). "In addition, a recent study has indentified METTL3 as a key regulator of ribosome levels and translation through distinct mechanisms in chronic myeloid leukemia." (PMID 40577453, 2025). "In contrast, in chronic myelocytic leukemia (CML), LINC00470 has been shown to bind METTL3 and positively regulate the m6A modification levels of PTEN mRNA, consequently downregulating ATG5 expression and leading to chemotherapy resistance." (PMID 39468015, 2024). "METTL3, the core methyltransferase involved in m6A modification, has been reported to play significant roles in normal hematopoiesis and hematological malignancies including AML, acute lymphocytic leukemia (ALL), chronic myeloid leukemia (CML), and lymphoma." (PMID 37280654, 2023). "In addition, the negative regulator of PI3K/AKT, PTEN, has been reported to be a direct target of METTL3 in HCC and chronic myelocytic leukemia (CML)." (PMID 34315512, 2021).
clear cell renal cell carcinoma (12 papers, 2019 to 2025). "Kaplan-Meier analysis showed that patients with increased METTL3 expression had a poor overall survival in TCGA Kidney Clear Cell Carcinoma (TCGA-KIRC) cohort, indicating its role in promoting kidney tumorigenesis." (PMID 34631715, 2021). "The frequent alteration of METTL3 was reported in clear cell renal cell carcinoma (ccRCC), implying that METTL3 had potential predictive values in ccRCC." (PMID 33879256, 2021). "One recent study reported a signature consisting of METTL14 and METTL3 as an independent prognosis factor in clear cell renal cell carcinoma." (PMID 33363211, 2020). "METTL3 was up‐regulated in clear cell renal cell carcinoma in comparison with normal samples." (PMID 32615646, 2020). "In conclusion, we built up a three-m6A methylation regulators-based RS of METTL3, METTL14 and HNRNPA2B1 that may become potential biomarker for prognosis prediction of clear cell renal cell carcinoma patients, our results call for further experimental studies for validations." (PMID 32219036, 2020).
Cognitive impairment (12 papers, 2021 to 2025). Abnormal cognition is characterized by deficits in thinking, reasoning, or remembering. "Together, our data show that m6A dysregulation, which is mediated by METTL3, most likely contributes to cognitive deficits linked to the hippocampus via the PD-1/PD-L1 pathway." (PMID 37234260, 2023). "Mechanistically, soluble Aβ oligomers caused a reduction in METTL3, whereas METTL3 overexpression rescued Aβ-induced synaptic damage, cognitive impairment, and postsynaptic density protein 95 (PSD95) loss in vitro." (PMID 37189411, 2023). "Specifically, METTL3 mediates the m6A modification of pri-miR-221, promoting its maturation and upregulating miR-221-3p, which inhibits Gab1 expression and exacerbates cognitive deficits related to depression." (PMID 40590504, 2025). "Studies in Alzheimer's disease models have shown that METTL3 stabilizes mRNAs to facilitate the clearance of phosphorylated Tau,52 and its overexpression in vivo reduces β‐amyloid‐induced synaptic damage and cognitive deficits." (PMID 41018232, 2025). "On the contrary, overexpression of METTL3 in vivo rescues synaptic damage and cognitive deficits induced by AβO." (PMID 37255714, 2023). "The brains of Mettl3−/− mice and Ythdf1−/− mice showed cognitive impairment similar to AD, in which the brains of Mettl3−/− mice showed microglia activation, and METTL3 overexpression mice prevented AβO-induced synaptic loss and cognitive impairment." (PMID 37255714, 2023). "The expression of METTL3 is decreased in the hippocampus of AD brain, leading to cognitive impairment, but its expression is increased in microglia, which has the role of promoting neuroinflammation." (PMID 37255714, 2023). "In a study of the role of Mettl3 in age-related neurodegenerative diseases, Mettl3 levels were reduced in the brains of patients with mild cognitive impairment, which is the prodromal phase of AD, as well as in AD patients." (PMID 37234260, 2023). "This was further strengthened by the findings that METTL3 overexpression fully rescued Aβ oligomers-induced synaptic deficits and cognitive deficits in vivo." (PMID 34593014, 2021). "More importantly, overexpression of METTL3 rescued Aβ oligomers-induced cognitive deficits in adult mice." (PMID 34593014, 2021). "The impact of surgical stress on m6A regulation further supports this connection, as experimental studies demonstrate that acute METTL3 knockout induces hippocampal cognitive deficits, highlighting its essential role in maintaining cognitive function during perioperative stress." (PMID 41018232, 2025). "The cognitive deficits in the Mettl3 knockdown group were due to a single factor, Mettl3." (PMID 37234260, 2023). "Moreover, overexpression of METTL3 ameliorated synaptic and cognitive impairments in rats treated with Aβ." (PMID 38012808, 2023). "Notably, the expression of METTL3 was significantly downregulated in the brains of patients with mild cognitive impairment." (PMID 36118889, 2022). "Overexpression of METTL3 in neurons salvaged Aβ-induced synaptic damage and cognitive impairment." (PMID 36118889, 2022). "Importantly, METTL3 overexpression rescued Aβ-induced synaptic damage and cognitive impairment in vivo." (PMID 34593014, 2021). "Importantly, METTL3 overexpression effectively rescued the AβOs-induced cognitive deficits in these mice." (PMID 34593014, 2021). "Decreased m6A modification by METTL3 knockdown in the hippocampus in vivo resulted in elevated oxidative stress, aberrant cell cycle events, activation of apoptosis and neurodegeneration as well as cognitive deficits similar to that of AD." (PMID 34593014, 2021). "Further mechanic study found that METTL3-mediated m6A modification on pri-miR-221 promoted its processing and maturation that subsequently upregulated miR-221-3p expression to inhibit GRB2-associated binding protein 1 (Gab1) expression, which worsened the cognitive deficits in MDD rats." (PMID 37189411, 2023).
Cognitive impairment (continued). "The m6A methyltransferase METTL3 is highly expressed in CUS-induced depressive rat models, and silencing METTL3 improves cognitive deficits." (PMID 40590504, 2025). "Furthermore, methyltransferase-like 3 (METTL3) elevated GPX4 levels by enhancing its mRNA stability, thereby suppressing ferroptosis and ameliorating cognitive impairment post-TBI." (PMID 41369366, 2025). "Moreover, silencing METTL3 by sh-METTL3 AAV ameliorated synaptic and cognitive impairments in 6-month-old APP/PS1 mice." (PMID 38012808, 2023).
ischemic heart disease (12 papers, 2020 to 2025). "For ischemic heart disease, METTL3 decreases the stability of transcription factor EB (TFEB) mRNA by increasing its m6A modification." (PMID 41446042, 2025). "In recent years, there has been increasing interest in investigating the relationship between METTL3-mediated m6A RNA methylation and ischemic heart diseases." (PMID 39893158, 2025). "This suggests that METTL3 behaves as a negative regulator of autophagy in ischemic heart diseases, while ALKBH5 functions oppositely." (PMID 38988324, 2024). "In fact, METTL3-mediated m6A RNA methylation may be a double-edged sword for ischemic heart diseases." (PMID 39893158, 2025). "Therefore, this study aims to investigate the role of METTL3-mediated m6A RNA methylation modification in the autophagy of ischemic and hypoxic cardiomyocytes, and explore the mechanism of m6A modification involved in ischemic heart diseases." (PMID 39893158, 2025). "Methyltransferase like 3 (METTL3) reverses the transcriptional activity of TFEB by binding to the 3’-UTR end of TFEB and concomitantly methylating two m6A residues, thus playing a protective role in ischemic heart disease." (PMID 33679452, 2021).
Myocardial fibrosis (12 papers, 2021 to 2025). "From the results, Masson’s Trichrome staining demonstrated more fibrosis in WT mice compared with CKO-METLL3 mice after MI, which showed that METTL3 deficiency reduced myocardial fibrosis." (PMID 36980863, 2023). "For example, ablation of METTL3 weakened MI-caused myocardial fibrosis by impeding the activation of cardiac fibroblasts." (PMID 34778266, 2021). "Collectively, these data establish that METTL3 could be an important molecular hallmark that may regulate myocardial fibrosis post‐MI by increasing m6A methylation." (PMID 40913254, 2025). "Results demonstrated increased levels of m6A methylation and METTL3 expression in myocardial fibrosis tissue post‐MI and in hypoxia‐treated cardiac fibroblasts." (PMID 40913254, 2025). "We applied STM2457 to inhibit the METTL3-mediated m6A modifications in these cells, evaluating the impact on myocardial fibrosis and cardiac remodeling." (PMID 38948064, 2024). "Underlining the molecular mechanisms of m6A in participating in myocardial fibrosis and remodeling, it pointed toward novel intervention strategies, including targeting METTL3 and METTL14 in peripheral blood monocytes." (PMID 38948064, 2024). "LncRNA MetBil up-regulates the expression of METTL3 through the ubiquitin-proteasome pathway, and METTL3-mediated modification of fibrosis-regulated genes by m6A modification regulates myocardial fibrosis occurrence." (PMID 39113708, 2024). "METTL3 facilitates mitochondrial fission by augmenting the methylation of lncRNA GAS5 to induce myocardial fibrosis." (PMID 38405130, 2024). "It has been reported that METTL3 overexpression activated CF deposition and promoted collagen synthesis and deposition, while its inhibition improved myocardial fibrosis and cardiac function." (PMID 37273867, 2023). "Also, the Masson staining demonstrated induction of myocardial fibrosis by METTL3 over-expression in MA treated TAC mice, which was evident by the elevated mRNA and protein expression of Fibronectin, Collagen I, and α-SMA." (PMID 35347085, 2022). "Subsequent histological analyses via HE staining and Masson trichrome staining revealed that METTL3-CKO mice showed greater survival of cardiomyocytes and reduced myocardial fibrosis compared to controls, with these effects reversed upon ATG7 knockdown." (PMID 39893158, 2025). "Overexpression of methyltransferase METTL3 in CFs could upregulate the expression of fibrosis‐related genes and activate the TGF‐β/Smad2/3 signalling pathway to promote the development of myocardial fibrosis." (PMID 40913254, 2025).
papillary thyroid cancer (12 papers, 2022 to 2025). "METTL3 deficiency enhances IL-8 production in papillary thyroid carcinoma cells, thereby promoting the recruitment of tumor-associated neutrophils." (PMID 40986143, 2025). "The METTL3–STEAP2 axis functions as a tumor suppressor in papillary thyroid carcinoma by inhibiting EMT program and suppressing hedgehog signaling through transcriptional repression of its effectors." (PMID 40986143, 2025). "Mechanistically, silencing METTL3 promoted the progression and dedifferentiation of papillary thyroid carcinoma (PTC) both in vivo and in vitro." (PMID 38993572, 2024). "In papillary thyroid cancer, METTL3 stabilizes STEAP2 RNA and positively regulates STEAP2 expression in an m6A-dependent manner, which inhibits the Hedgehog signaling pathway and suppresses cancer metastasis." (PMID 37996892, 2023). "In the tumor microenvironment of papillary thyroid carcinoma, METTL3 could regulated the NEU infiltration through its downstream m6A target genes." (PMID 38049811, 2023). "However, in papillary thyroid carcinoma, METTL3 directly destabilizes c-Rel mRNA by increasing m6A levels and, together with YTHDF2, inactivates the NF-KB pathway and increases IL-8 secretion to induce neutrophil infiltration." (PMID 37996892, 2023). "Correlation analysis of immune cells and genes showed the highest negative correlation for YTHDF2/neutrophil in blood samples; consistent with one study that found METTL3 cooperating with YTHDF2 can inhibit papillary thyroid cancer progression via m6A/c-Rel/IL-8-mediated neutrophil infiltration." (PMID 36457545, 2022). "Thus, METTL3 can act as a tumor suppressor in papillary thyroid cancers." (PMID 36835633, 2023). "METTL3 stabilized STEAP2 metallo reductase (STEAP2) mRNA and increased STEAP2 expression in an m6A-dependent manner in papillary thyroid cancer cells." (PMID 36835633, 2023). "In papillary thyroid cancer (PTC), METTL3 restrained PTC progression via m6A/c-Rel/IL-8-mediated neutrophil infiltration." (PMID 36008805, 2022).